CRP (C-reactive protein)
Diseases named in the same sentence as CRP in open-access papers (continued):
Sharing a sentence is not in itself a finding about the gene and the disease.
Arrhythmogenic right ventricular dysplasia (4 papers, 2010 to 2024). "Elevated CRP levels have also been reported in Arrhythmogenic Right Ventricular Dysplasia/Cardiomyopathy (ARVD/C), while another study reported higher CRP values for cases with constructive pericarditis than those with restrictive cardiomyopathy." (PMID 37873776, 2023).
autosomal dominant polycystic kidney disease (4 papers, 2021 to 2024). Autosomal dominant form of polycystic kidney disease. "In case of patients with ADPKD (autosomal dominant polycystic kidney disease)—the presence of inflammatory reaction (measured by an increase of CRP) significantly increases the adherence of monocytes to the biofilm." (PMID 34580787, 2021).
behavioral problems (4 papers, 2022 to 2025). "Children with externalizing behavioral problems have elevated levels of C-reactive protein (CRP) and interleukin 6 (IL-6)." (PMID 37783687, 2023). "CRP is an acute phase protein that is widely used in clinical practice and has also been measured in many previous studies of behavioral disorders." (PMID 35795852, 2022). "We observed remarkable differences between the two groups at ICU admission, consciousness dysfunction, psychiatric disturbance, autonomic nerve dysfunction, neutrophils, eosinophils, FARP, Fib, D-dimer, and CRP (P < 0.05)." (PMID 36908596, 2023).
Bradycardia (4 papers, 2021 to 2022). A slower than normal heart rate (in adults, slower than 60 beats per minute). "While age, CRP, and bradycardia were associated with in-hospital mortality in those aged less than 65 years, only CRP was associated with in-hospital mortality in those aged 65 years and above." (PMID 35251855, 2022). "While age, CRP, and bradycardia were associated with mortality in those aged less than 65 years, only CRP was associated with mortality in those aged 65 years and above." (PMID 35251855, 2022). "Furthermore, in patients aged 65 years and above, age (hazard ratio (HR) = 1.05; p < 0.001), C-reactive protein (CRP) (HR = 1.05; p < 0.001), and bradycardia (HR = 2.1; p < 0.001) were significantly associated with mortality." (PMID 35251855, 2022). "LDH and CRP were also significantly higher in the marked bradycardia group versus normal HR group." (PMID 33964035, 2021). "The patients with bradycardia had greater levels of erythrocyte sedimentation rate (ESR) and C-reactive protein (CRP)." (PMID 35888669, 2022). "Interestingly, the patients with bradycardia had a higher level of inflammatory markers including ESR and CRP." (PMID 35888669, 2022). "Nevertheless, the CRP levels were not suggestive of developing bradycardia in patients in the present study (p-value = .41)." (PMID 36733376, 2022).
breast tumor (4 papers, 2011 to 2023). "Aggressiveness of the breast tumor can be estimated by the relative increase of CRP levels at the time of diagnosis." (PMID 32532068, 2020). "Second, adjacent inflammation: plasma CRP levels might express the magnitude and the nature of any inflammation in the breast tumour microenvironment." (PMID 21639875, 2011).
bruxism (4 papers, 2021 to 2025). Excessive clenching of the jaw and grinding of the teeth. "Our correlation analysis (r = 0.364 between BSQ and QRISK3) aligns with prior work showing moderate associations (r ≈ 0.30-0.40) between bruxism severity and CRP, fibrinogen, or ambulatory blood pressure fluctuations." (PMID 41141201, 2025). "More related evidence about this in SB has emerged recently, when researchers found that the concentrations of the inflammatory markers in urine samples, including 17-hydroxycorticosteroids, C-reactive protein, and fibrinogen, were positively associated with the bruxism episode index." (PMID 38125907, 2023).
Castleman disease (4 papers, 2022 to 2024). Castleman disease (CD) is a benign lymphoproliferative disorder that may present as a localized or multicentric form. "Univariate analysis indicated that both PNP and the elevation of C-reactive protein (CRP) were negative indicators of survival in patients with Castleman disease." (PMID 39649406, 2024). "Moreover, a study reported immune dysfunction and increased CRP in children with Castleman’s disease, but another study did not report a CRP increase for all of the participants." (PMID 37873776, 2023).
central retinal artery occlusion (4 papers, 2020 to 2026). "We were also able to evaluate the diagnostic accuracy of further features, including transient loss of vision, cerebrovascular accident, limb claudication, central retinal artery occlusion, CRP levels, and platelet counts." (PMID 32804186, 2020).
cerebral embolism (4 papers, 2020 to 2025). "This study explored the association between inflammatory biomarkers—C-reactive protein to albumin ratio (CAR), platelet to lymphocyte ratio (PLR), and neutrophil to lymphocyte ratio (NLR)—and the prognosis of patients with cardiogenic cerebral embolism (CCE)." (PMID 40599820, 2025). "Hence, high molecular mucin markers such as CA 125 and CA 19–9 can be important markers, whereas the elevated D-dimer and C-reactive protein levels are reported to be useful for diagnosis of Trousseau’s syndrome in patients with cerebral embolism." (PMID 32388737, 2020).
chronic kidney failure (4 papers, 2020 to 2024). "Some studies have shown that an increase in CRP is associated with a decrease in creatinine clearance in pre-dialysis chronic kidney failure patients and may serve as a risk marker for kidney function impairment." (PMID 38386646, 2024).
chronic thromboembolic pulmonary hypertension (4 papers, 2020 to 2023). Chronic thromboembolic pulmonary hypertension (CTEPH) is characterized by the persistence of thromboemboli in the form of organized tissue obstructing the pulmonary arteries. "Another work described the use of proximal pulmonary arterial ECs for the study of C-reactive protein (CRP) in chronic thromboembolic pulmonary hypertension (CTEPH)." (PMID 32887493, 2020). "Importantly, in patients with idiopathic PAH or chronic thromboembolic pulmonary hypertension, CRP correlated with NYHA class, right atrial pressure, and the six-minute walking test distance." (PMID 37176542, 2023).
coccidioidomycosis (4 papers, 2019 to 2023). A fungal infection caused by Coccidioides immitis. "Dogs with coccidioidomycosis had higher constitutive plasma keratinocyte chemotactic (KC)-like concentrations (p = 0.02) and serum CRP concentrations compared to controls (p < 0.001)." (PMID 36836327, 2023). "A preliminary investigation of CRP in dogs with coccidioidomycosis is justified before larger and more extensive studies evaluating the clinical utility and interactions with the host immune response are pursued." (PMID 36836327, 2023). "antigen-stimulated leukocyte cytokine production to assess the inflammatory profile, TLR2 and TLR4 expression, and serum CRP concentrations between dogs with newly diagnosed coccidioidomycosis and seronegative healthy controls." (PMID 36836327, 2023). "Taken together, CRP has intriguing potential not only as a biomarker but also as a component in the host immune response in dogs with coccidioidomycosis." (PMID 36836327, 2023). "Collectively, these results provide the rationale for future studies to investigate the clinical utility and biological activity of CRP in dogs with coccidioidomycosis." (PMID 36836327, 2023). "Similarly, dogs with pulmonary coccidioidomycosis had higher serum CRP concentrations than those with disseminated disease (p = 0.001)." (PMID 36836327, 2023). "Dogs with coccidioidomycosis had higher serum CRP concentrations than controls (p < 0.001)." (PMID 36836327, 2023). "Moreover, dogs with pulmonary coccidioidomycosis had higher serum CRP concentrations than those with dissemination (p = 0.001)." (PMID 36836327, 2023). "Dogs with coccidioidomycosis had higher serum CRP concentrations than controls." (PMID 36836327, 2023). "We hypothesized that cytokine concentrations, serum CRP concentration, and leukocyte TLR2 and TLR4 expression would be different between dogs with coccidioidomycosis and healthy controls." (PMID 36836327, 2023). "Ours was a preliminary investigation of CRP in dogs with coccidioidomycosis and thus its role in the host immune response was not explored." (PMID 36836327, 2023). "Serum CRP concentrations are commonly elevated in humans with coccidioidomycosis; however, there have been no published studies that have investigated its clinical value as a biomarker." (PMID 36836327, 2023). "Erythrocyte sedimentation rates and C-reactive protein, though not sensitive or specific to coccidioidomycosis, are frequently elevated." (PMID 31284663, 2019). "We also identified CRP as a negative predictor for coccidioidomycosis." (PMID 35608552, 2022). "Our univariable analyses for inpatients identified negative associations with age, muscle aches, immunocompromised status, and CRP with coccidioidomycosis positivity, but non-White racial status, rash, eosinophil count, and total protein were positive predictive markers of disease." (PMID 35608552, 2022). "Laboratory markers including PCT, CRP, and ESR were significantly lower in coccidioidomycosis-positive than -negative participants (p<0.001)." (PMID 35608552, 2022).
Cyanosis (4 papers, 2014 to 2025). Bluish discoloration of the skin and mucosa due to poor circulation or inadequate oxygenation of arterial or capillary blood. "In contrast, reports for the hexavalent vaccine described a broader range of serious neurological and systemic reactions, including cyanosis, loss of consciousness, elevated C-reactive protein, high fever, musculoskeletal rigidity, and movement disorders." (PMID 41245254, 2025).
dysentery (4 papers, 2013 to 2024). Acute inflammation of the intestine associated with infectious diarrhea of various etiologies, generally acquired by eating contaminated food containing toxins, biological derived from bacteria or other microorganisms. "Young age, the presence of dysentery, higher levels of CRP, and performing blood cultures were positively associated with appropriate antibiotic use." (PMID 38247623, 2024). "The correlates of appropriate antibiotics were younger age, having dysentery, CRP level, and performing blood culture." (PMID 38247623, 2024). "Having dysentery (OR = 5.30 [95% CI 3.35–8.39]), performing blood culture (OR = 1.59 [95% CI 1.02–2.48]), and C-reactive protein (CRP) levels (OR = 1.01 [95% CI 1.01–1.02]) were positively associated with receiving appropriate antibiotic treatment." (PMID 38247623, 2024).
dyspepsia (4 papers, 2013 to 2023). An uncomfortable, often painful feeling in the stomach, resulting from impaired digestion. "Fourteen genes corresponding to two gene sets were identified, and the functional dyspepsia-related genes targeted by the activated F. fructus compound were ADRA2A, BDNF, CCK, CRP, GCG, JUN, Kcnh2, PTGS1, PTGS2, Pyy, SLC6A4, and TRPV." (PMID 37375548, 2023).
dysplasia (4 papers, 2019 to 2025). A usually neoplastic transformation of the cell, associated with altered architectural tissue patterns. "For example, the OR for the association between CRP and GBC was 1.69 (95% CI: 0.86–3.34), whereas the association with dysplasia was inverse (OR: 0.71, 95% CI: 0.54–0.95)." (PMID 39482824, 2025). "Contrary to our expectations, current use of NSAIDs was associated with increased levels of sVEGFR3 and GRO in controls and with high levels of CRP in dysplasia cases after adjustment for age, sex, and surgery type." (PMID 39482824, 2025). "After including sVEGRF3, GRO and CRP (the immune‐related markers associated with current use of NSAIDS) in the model, the association between NSAID use and dysplasia was attenuated (OR: 0.79, 95% CI: 0.36–1.68)." (PMID 39482824, 2025). "Eight of the 33 immune‐related markers (IL‐33, BCA‐1, GRO, CCL19 (MIP‐3B), sTNFRII, CXCL6 (GCP2), CRP and MIP‐1B) were inversely associated with dysplasia, with univariate ORs ranging from 0.30 (95%CI: 0.12–0.77) for IL‐33 to 0.76 (95%CI: 0.59–0.99) for MIP‐1B." (PMID 39482824, 2025). "After adjusting for categorical age, sex and surgery type, current use of NSAIDs was associated with increased levels of sVEGFR3 (OR: 2.61, 95% CI: 1.12–6.33) and GRO (OR: 2.55, 95% CI: 1.11–6.01) in controls and with higher levels of CRP (OR: 4.61, 95% CI: 1.47–15.64) in dysplasia cases." (PMID 39482824, 2025). "Serum CRP levels have been reported to predict dysplasia progression and similar proteomic or metabolomic biomarkers may be useful for identifying participants with endobronchial dysplasia." (PMID 37711198, 2023).
E. coli infection (4 papers, 2019 to 2021). "In this study, the untreated healthy control pigs had infected with gut pathogens E. coli infection and showed significantly higher plasma CRP level, and lower level of compliment and phagocytic activity in peripheral blood when compared to all groups pig fed with immunobiotic feed supplements." (PMID 33803393, 2021). "According to the authors, lower levels of CRP (median value: 33 mg/dl), higher levels of NLR (over 3.5) and higher levels of urine IL-8 (uIL-8) (median: 2,120 pg/ml) refer to extended spectrum beta-lactamase (ESBL) producing Escherichia coli infection." (PMID 33299741, 2020).
enterocolitis (4 papers, 2022 to 2024). An inflammatory process affecting the small intestine and colon. "Subsequently, the infant developed grade II-a enterocolitis on day 17, with elevated CRP (45.3 mg/L) and a positive blood culture." (PMID 39511443, 2024). "Laboratory tests, including complete blood count, serum electrolyte panel, C-reactive protein (CRP), cytomegalovirus PCR, and stool analysis for enteropathogens and clostridium difficile toxin, aid in assessing the severity of the enterocolitis and to rule out other causes." (PMID 39061225, 2024). "The patient had grade II-a enterocolitis from days 9 to 16, without inflammation or elevated CRP documented, corresponding to a rising TSB episode." (PMID 39511443, 2024).
enterovirus infection (4 papers, 2018 to 2025). "This indicated that elevated CRP level was the strongest risk factor for prescription of antibiotics in children experiencing enterovirus infection." (PMID 30192893, 2018). "Although our study had only one case of GAS infection, HSV, adenovirus, and enterovirus infections also had high CRP levels, with 26.1–41.5% of these cases having a CRP value higher than 100 mg/L." (PMID 40142520, 2025). "We conclude that better appraisal of serum CRP level would result in better quality healthcare for patients experiencing enterovirus infection, and possibly prevent serious neurologic complications." (PMID 30192893, 2018). "In contrast, for enteroviral infection, a retrospective study including 3566 children with a diagnosis of either herpangina or HFMD in Taiwan revealed that three quarters of the cases had a CRP level < 40 mg/L while only 6% cases had a CRP level > 80 mg/L." (PMID 33081701, 2020).
essential thrombocythemia (4 papers, 2014 to 2023). A chronic myeloproliferative neoplasm that involves primarily the megakaryocytic lineage. "Moreover, some other data have linked CRP elevation with myeloproliferative disorders, and other data have revealed a possible CRP SNP association with certain myeloproliferative neoplasms (primary myelofibrosis and essential thrombocythemia)." (PMID 37873776, 2023).
Gastrointestinal hemorrhage (4 papers, 2014 to 2025). Hemorrhage affecting the gastrointestinal tract. "Levels of inflammatory parameters (C-reactive protein, leukocyte counts in blood and ascites), nosocomial origin of infection, presence of indwelling catheters and the presence of acute gastrointestinal bleeding in the context of SBP were comparable between the groups." (PMID 24714550, 2014).
Giardia infections (4 papers, 2014 to 2024). "In children populations from developing countries, Giardia infections also have been found to reduce the incidence of diarrheal disease and fever, and decrease serum C-reactive protein (CRP) levels, which is a common marker of inflammation." (PMID 26569316, 2015). "Human studies have demonstrated that Giardia infections reduce serum levels of serum CRP, thereby indicating that these infections are capable of modulating systemic immune responses." (PMID 26569316, 2015). "Indeed, it is suggested a reduction or absence of inflammation with Giardia infection, a decrease in subsequent rates of diarrhea and fever, as well as lower systemic levels of C-reactive protein in children." (PMID 38768226, 2024).
hemorrhagic fever (4 papers, 2018 to 2025). An infectious disease caused by certain viruses or bacteria that can damage the walls of tiny blood vessels, making them leak, and can hamper the blood's ability to clot and cause severe, life-threatening illness. "Serological and C-reactive protein test results for Crimean-Congo hemorrhagic fever were positive." (PMID 29724249, 2018).
Hepatomegaly (4 papers, 2017 to 2025). Abnormally increased size of the liver. "CRP over 30 mg/L, ESR over 40 mm/h, Hepatomegaly and IVIG-ineffectiveness were high risk factors of typical KD." (PMID 28903347, 2017).
hydatid disease (4 papers, 2012 to 2025). "Elevated eosinophil counts, increased C-reactive protein levels, and positive Echinococcus antibodies pointed toward hydatid disease, confirmed by imaging showing multiple cystic lesions in the lungs and liver." (PMID 40818408, 2025). "Pain in the right upper quadrant is the major clinical symptom (up to 88% of cases), followed by a high temperature (>39 °C) in up to 78% of cases, while elevated C-reactive protein (CRP) acts as a predictor of a complex hydatid disease." (PMID 38921947, 2024). "The mean CRP level was 5.0 (7.3) mg/dl in the cancerous patients and 4.9 (5.5) mg/dl (p = 0.59; NS) in those suffering from echinococcosis." (PMID 22340429, 2012). "In echinococcosis there was a correlation between the sE-CAD and CRP levels (rs = 0.79; p = 0.0066) as well as a correlation between the sE-CAD level and the number of leukocytes (rs = 0.65; p = 0.0210) in the blood." (PMID 22340429, 2012). "Moreover, in echinococcosis, there was a correlation between the sE-CAD and CRP levels (rs = 0.79; p = 0.0066) as well as a correlation between the sE-CAD level and the number of leukocytes (rs = 0.65; p = 0.0210) in the blood." (PMID 22340429, 2012).
hypogonadism (4 papers, 2014 to 2024). A disorder characterized by decreased function of the gonads. "Studies have shown that higher CRP levels are associated with lower testosterone levels, reinforcing the link between inflammation and hypogonadism." (PMID 39473678, 2024). "One common observation in these studies is that higher levels of IL-6, IL-1β, TNF-α, and CRP were noted in men with testosterone deficiency (hypogonadism)." (PMID 30558178, 2018). "The strong predictive value of CRP on Free Testosterone levels (R-squared = 0.674) indicates that inflammation is a major determinant of hypogonadism in this population." (PMID 39473678, 2024). "Regression analysis further confirmed that CRP was a significant predictor of free testosterone levels (R-squared = 0.674), emphasizing the crucial role of inflammation in the pathophysiology of hypogonadism in obese individuals." (PMID 39473678, 2024). "Additionally, the study emphasizes the crucial role of chronic inflammation, particularly CRP, as a predictor of hypogonadism, underscoring the pathophysiological link between adiposity and hormonal imbalance." (PMID 39473678, 2024). "The strongest negative correlation observed was between CRP and free testosterone (r = -0.82), highlighting the impact of chronic inflammation on hypogonadism." (PMID 39473678, 2024).